CHD7 (chromodomain helicase DNA binding protein 7)
Diseases named in the same sentence as CHD7 in open-access papers (continued):
Sharing a sentence is not in itself a finding about the gene and the disease.
congenital heart disease (7 papers, 2014 to 2025). A heart disease that is present at birth. "A study involving 299 patients with pathogenic CHD7 mutations shows that 74% of these patients have heart defects." (PMID 36568983, 2022). "Having defined parameters that permit efficient Cas9-mediated gene knockout in mESCs, we next targeted Smad2, MLL2, and CHD7, mutations of which have been implicated in human congenital heart disease." (PMID 25166277, 2014).
developmental delay (7 papers, 2009 to 2025). "Upon differentiation towards the forebrain neuronal lineage, neural cells carrying the CHD7 intronic variant exhibited developmental delay and maturity defects." (PMID 33948885, 2021). "Focusing on ENT-related symptoms and signs in patients with a CHD7 pathogenic/likely pathogenic variant, the most prevalent include inner ear anomalies, external ear anomalies, hearing loss, cranial nerve dysfunction, and developmental delay." (PMID 38790272, 2024). "Developmental delay in patients with CCH can be attributed to syndromes involved in cerebral abnormalities like midline brain defects, or to mutations in genes like IGSF1 or CHD7 that are associated with neurologic involvement." (PMID 39008607, 2025).
Intellectual disability (7 papers, 2016 to 2023). "In addition to CHD3, CHD4 and CHD5, other highly related members of the CHD superfamily, CHD2, CHD7 and CHD8 have also been implicated in ASD and intellectual disability." (PMID 37190088, 2023). "Mutations of CHD7 are found in patients affected by CHARGE syndrome, a severe clinical condition that affects many organs and is associated with deafness, blindness and often various degrees of intellectual disability." (PMID 37190088, 2023).
hypogonadism (6 papers, 2011 to 2024). A disorder characterized by decreased function of the gonads. "For the first time, we demonstrate that a KS patient with a truncating CHD7 mutation can undergo reversal of hypogonadotropism." (PMID 22724017, 2012). "Concerning variant recurrence, the heterozygous mutation in FGFR1 p.R285W (likely pathogenic; CM063987 HGMD), coexisting with another heterozygous variant CHD7 p.N1030H (pathogenic; novel), was recurring in two unrelated patients, both with reversal of hypogonadism." (PMID 34198905, 2021). "Patients with IHH/KS and defects in CHD7 should be significantly monitored for a reversal of hypogonadism." (PMID 34198905, 2021). "In a long-term clinical follow-up, three unrelated subjects with digenic defects (proband 9: CHD7 p.N1030H and FGFR1 p.R285W; proband 10: CHD7 p.N1030H and FGFR1 p.R285W; and proband 25: GNRHR p.R139H, GNRHR p.N10_Q11delinsKK, and CHD7 p.K683_T684insAK) displayed a reversal of hypogonadism." (PMID 34198905, 2021).
hypospadias (6 papers, 2017 to 2024). Hypospadias is the displacement of the urethral meatus on the ventrum of the penis. "Patient 4 harbored CHD7 mutation, and CHD7 plays an important role in gonad development and signaling, and mutation could cause hypospadias in previous study." (PMID 35669683, 2022). "We postulate that variants in CHH genes, in particular PROKR2, PROK2, WDR11 and FGFR1 with CHD7, may contribute to under-virilisation phenotypes including hypospadias in Indonesia." (PMID 28209183, 2017). "We conclude that variants in CHH genes, in particular PROKR2, PROK2, WDR11 and FGFR1 with CHD7, may contribute to under-virilisation phenotypes including hypospadias in Indonesian boys." (PMID 28209183, 2017).
congenital hypogonadotropic hypogonadism (4 papers, 2019 to 2022). Congenital hypogonadotropic hypogonadism (CHH) is a rare disorder of sexual maturation characterized by gonadotropin (Gn) deficiency with low sex steroid levels associated with low levels of follicle stimulating hormone (FSH) and luteinizing hormone (LH). "Other variants were identified in genes know to be associated with congenital hypogonadotropic hypogonadism (CHH), including the CHD7 and PROKR2 genes." (PMID 36110220, 2022).
epilepsy (4 papers, 2017 to 2022). A brain disorder characterized by episodes of abnormally increased neuronal discharge resulting in transient episodes of sensory or motor neurological dysfunction, or psychic dysfunction. "Using qRT–PCR, we validated the downregulation of ASD-related genes involved in cerebellar development (Cadps2 and Reln) (refs 28, 43), and ASD- or epilepsy-related ion channels in neurons (Cacna2d1, Grik2 and Kcnd2) (refs 43, 44, 45) in ICRF-193 treated or Chd7 mutant CGNs." (PMID 28317875, 2017).
glioblastoma (4 papers, 2016 to 2022). The most malignant astrocytic tumor (WHO grade IV). "Consistent with the role exerted during neural development, CHD7 is also implicated in tumors affecting CNS and NC-derived tissues, including medulloblastoma, glioblastoma, and neuroblastoma (see Chapter 5)." (PMID 33869187, 2021). "Initially, we set out to investigate the effect of CHD7 loss-of-function in glioblastoma lines naturally expressing high levels of CHD7." (PMID 30850678, 2019). "It will be of great interest to investigate, for example, the underlying mechanism regulating differential CHD7 expression in glioblastoma cells and whether these pathways are amenable to manipulation by molecular intervention aiming at clinical therapeutic trials." (PMID 30850678, 2019). "Conversely, ectopic overexpression of CHD7 in LN-428 and A172 glioblastoma cell lines increases cell motility and invasiveness in vitro and promotes LN-428 tumor growth in vivo." (PMID 30850678, 2019). "We found that CHD7 is expressed in the vast majority of human glioblastoma-derived cell lines in vitro." (PMID 30850678, 2019). "Our data provides functional and molecular evidences for a novel oncogenic role of CHD7 as a transcriptional regulator of pro-invasive and motility factors in glioblastoma cells." (PMID 30850678, 2019). "We next analyzed CHD7 mRNA and protein levels in a panel of eight human long-term glioblastoma cell lines (LTCs) and five GIC lines." (PMID 30850678, 2019). "In vitro, CHD7 expression was found to be highly heterogeneous in the panel of human glioblastoma-derived cell lines analyzed consistent to what we observed in our set of clinical samples as well as in the TCGA public database." (PMID 30850678, 2019). "Using a candidate gene approach, we set out to investigate a possible role for CHD7 in glioblastoma, given its pivotal role for NSC function and the evidence for CHD7 alterations in other tumor types." (PMID 30850678, 2019). "Together, these data strongly indicate that CHD7 plays an important role in glioblastoma cell migration and invasion." (PMID 30850678, 2019). "Next, we examined the presence of CHD7 expressing cells by immunohistochemistry in glioblastoma patient samples." (PMID 30850678, 2019). "In silico analysis shows that CHD7 and CHD9 are well expressed in brain tumor, and CHD7 is expressed highly in Glioblastoma multiforme (GBM) compared to normal brain." (PMID 27955690, 2016). "Although CHD7 expression was not significantly correlated to patient prognosis, the great heterogeneity within glioblastoma tumors prompted us to further examine the functional impact of CHD7 in glioblastoma cells endogenously expressing contrasting levels of this protein." (PMID 30850678, 2019). "However, the potential contribution of CHD7 to glioblastoma tumor biology had not yet been tested." (PMID 30850678, 2019).
medulloblastoma (4 papers, 2017 to 2025). A malignant, invasive embryonal neoplasm arising from the cerebellum. "Next, we screened primary human medulloblastoma samples for CHD7 mutations." (PMID 29212025, 2017). "find convergence of the chromatin modifiers BMI1 and CHD7 in medulloblastoma pathogenesis, and they show that this pathway regulates tumor proliferation and growth via ERK signaling." (PMID 29212025, 2017). "Notably, 37 of the superenhancers had known Group 3 and 4 medulloblastoma drivers as their nearest genes, including CHD7, CBFA2T2, GSE1, and of course, OTX2, and ZIC1." (PMID 41279093, 2025). "We describe molecular convergence between BMI1 and CHD7 in the initiation of medulloblastoma." (PMID 29212025, 2017).
melanoma (4 papers, 2017 to 2025). A malignant, usually aggressive tumor composed of atypical, neoplastic melanocytes. "We found that CHD7 was mutated in more than 5% of eight tumor types, namely bladder, stomach, uterine, and cervical cancers, as well as cholangiocarcinoma, lung squamous cell carcinoma, lung adenocarcinoma, and melanoma." (PMID 28649742, 2017). "Furthermore, among 10 845 TCGA tumor samples, CHD7 had high‐level amplification in 362 cases (0.9%), in which five tumor types, namely breast, ovarian, uterine, and liver cancers and melanoma, exhibited CHD7 amplification in more than 5% of cases." (PMID 28649742, 2017).
microphthalmia (4 papers, 2008 to 2025). Congenital or developmental anomaly in which the eyeballs are abnormally small. "Further sequence analysis of other genes associated with anophthalmia and microphthalmia such as PAX6, BCOR, OTX2, SIX6, and CHD7 is ongoing in this study cohort to determine mutation associations." (PMID 18385794, 2008).
pancreatic cancer (4 papers, 2014 to 2023). "Low CHD7 expression leads to enhanced survival of pancreatic cancer patients, suggesting that CHD7 promotes oncogenesis." (PMID 36473865, 2022).
Feingold syndrome (3 papers, 2011 to 2022). Feingold syndrome (FS), also known as oculo-digito-esophageal-duodenal (ODED) syndrome, is a rare inherited malformation syndrome characterized by microcephaly, short stature and numerous digital anomalies and is comprised of two subtypes: FS type 1 (FS1) and FS type 2 (FS2). "In fact Pax is located in chromosome 11p13, Foxd11 on 5q12-13, Mycn (producing Feingold syndrome) on 2p24.1, Chd7 (CHARGE) on 8q12.2 and Sox2 (AEG) on 3q26." (PMID 21806818, 2011).
gastric cancer (3 papers, 2014 to 2021). A primary or metastatic malignant neoplasm involving the stomach. "On the other hand, low CHD7 levels correlate with an enhanced survival rate of patients with pancreatic tumor, and loss-of-function mutations of CHD7 are reported in colorectal as well as gastric cancer." (PMID 33869187, 2021).
lung adenocarcinoma (3 papers, 2017 to 2022). A carcinoma that arises from the lung and is characterized by the presence of malignant glandular epithelial cells. "Among the nine CHD members, CHD7 is the most commonly mutated gene in lung adenocarcinoma and squamous cell carcinoma, with a mutation frequency of 6%." (PMID 35467222, 2022). "Compared to normal samples, CHD7 was overexpressed in large cell lung carcinoma with a fold change of 2.741, papillary lung adenocarcinoma with a fold change of 1.162, and lung adenocarcinoma with a fold change of 1.491." (PMID 35467222, 2022). "Furthermore, higher CHD7/8 expression was significantly correlated with poor OS and FP in all patients with lung adenocarcinoma and, to a lesser extent, lung squamous cell carcinoma." (PMID 35467222, 2022). "Finally, cellular experiments conducted in vitro confirmed that CHD7/8 played indispensable roles in DNA damage signaling and cell cycle progression in lung adenocarcinoma cells." (PMID 35467222, 2022). "The oncogenic role of CHD7 in lung adenocarcinoma was also verified." (PMID 35789070, 2022). "Additionally, CHD7 is the most commonly amplified in lung adenocarcinoma." (PMID 35467222, 2022). "Finally, the potential biological roles of two CHD family members, CHD7 and CHD8, were illustrated in lung adenocarcinoma cells using experimental data." (PMID 35467222, 2022).
Anxiety (2 papers, 2022). Intense feelings of nervousness, tension, or panic often arise in response to interpersonal stresses. "In contrast to CHARGE patients with only one mutant allele of CHD7, chd7 heterozygous mutant fish do not display obvious phenotypes, except for the anxiety-like and aggressive behavior." (PMID 36568983, 2022). "Hence, Chd7+/Whi either exhibit resistance to anxiety or this is the result of increased hyperactivity." (PMID 36232804, 2022). "Mice on a C3HeB/FeJ background (which is the case of the Chd7+/Whi mutant) are qualified as anxious and “jumpy” mice by the Jackson laboratory which, incidentally, makes them better models to evaluate anxiety resistance (but not hypersensitivity)." (PMID 36232804, 2022).
atrioventricular septal defects (2 papers, 2016 to 2023). "It is recently reported that conotruncal defects and atrioventricular septal defects are overrepresented in patients with CHD7 mutations compared with patients with nonsyndromic heart defects." (PMID 27957375, 2016).
B-cell lymphomas (2 papers, 2020 to 2025). "Of the CHD subfamily III, CHD7 regulates developmental hematopoiesis and expansion of hematopoietic stem and progenitor cells, whereas CHD8 is required for survival of both non-transformed pre-B cells and acute lymphoblastic B-cell leukemia cells as well as EμMyc B-cell lymphomas." (PMID 32453735, 2020).
BAFopathies (2 papers, 2023 to 2024). "Notably, JARID2 exhibited the highest overlap with CHARGE (~7%, CHD7), BAFopathy (~4%, including ARID1A, ARID1B, SMARCB1, SMARCA2, SMARCA4), and the PCR2 complex, which houses Cohen–Gibson syndrome (COGIS) and Weaver syndrome (WVS) (~4%, EED, EZH2)." (PMID 37762546, 2023).
brain tumor (2 papers, 2016 to 2021). "Now, emerging data are beginning to highlight the contribution of CHD7–semaphorins network in the pathogenesis of brain tumors." (PMID 33869187, 2021). "In silico analysis in the present showed the higher expression of CHD7 and CHD9 in brain tumor." (PMID 27955690, 2016). "These seemingly contrasting data for SEMA3G may be explained by the high molecular heterogeneity of GBM cell lines and by the fact that high-CHD7-expressing cells specifically correspond to cells not expressing CD133, a marker of brain tumor-initiating cells." (PMID 33869187, 2021).
Cerebellar hypoplasia (2 papers, 2017). Cerebellar hypoplasia is a descriptive term implying a cerebellum with a reduced volume, but a normal shape and is stable over time. "We report here that adult GCp-specific Chd7 cko mutant mice with cerebellar hypoplasia exhibit a range of behavioral deficits." (PMID 28165338, 2017).
Cornelia de Lange syndrome (2 papers, 2024). A rare syndrome characterized by low birth weight, delayed growth, intellectual disabillity, behavioral problems, and a distinctive facial appearance (thin, arched eyebrows, low set ears, small teeth, and small nose). "Estimations of Sanger sequencing prices were performed for five genes most commonly associated with RASopathies (BRAF, NF1, PTPN11, RAF1, and SOS1), and three genes, TCOF1, CHD7, and NIBPL most commonly associated with Treacher Collins, CHARGE, and Cornelia de Lange syndromes, respectively." (PMID 37815686, 2024). "Remaining Cornelia de Lange syndrome, KMT2A, KDM5C and CHD7 signatures reached 70–100% sensitivity at best with unstable performances, suffering from heterogeneous methylation profiles among cases and rare discordant samples." (PMID 37872275, 2024).
gonadal dysgenesis (2 papers, 2022 to 2024). A congenital disorder characterized by the presence of extremely hypoplastic gonads preventing the development of secondary sex characteristics. "The CHD7 variant (p.L2806V) was classified as likely pathogenic in 3 unrelated patients (DSD cases 41, 45 and 62) raised as male, and the pathogenic DHX37 variant (p.R308Q) was carried by 2 patients (DSD cases 6 and 8) presented with gonadal dysgenesis and raised as male." (PMID 36110220, 2022).
Heart defects (2 papers, 2019 to 2021). "Patent ductus arteriosus is more commonly seen in patients with CHD7 pathogenic variants than nonsyndromic heart malformations." (PMID 31146700, 2019).
idiopathic scoliosis (2 papers, 2012 to 2020). A scoliosis with no known cause. "Although the CHD7 was the first described gene linked to idiopathic scoliosis, there are only two studies concerning polymorphisms of this gene in IS." (PMID 31924193, 2020). "Recently, CHD7 gene polymorphisms were associated with susceptibility to idiopathic scoliosis in human populations." (PMID 22363697, 2012).
immunodeficiencies (2 papers, 2020 to 2023). "In our patient, WES analysis focusing on a gene panel linked to immunodeficiencies identified two variants (c.1132A>G substitution in GATA2, c.8287_8295dup in CHD7) likely ascribed to have a negative impact on the immune system." (PMID 37959410, 2023).
lung carcinoma (2 papers, 2022). "The expression of CHD7/8 in lung cancer tissues was higher than that in normal tissues." (PMID 35467222, 2022). "Six hub genes were screened in relation to lung cancer, including mTOR, NF1, CHD7, ETS1, IL-6, and COL1A1." (PMID 36211008, 2022). "Further verification found that six hub genes were screened in relation to lung cancer, including mTOR, NF1, CHD7, ETS1, IL-6, and COL1A1." (PMID 36211008, 2022). "Then, we selected CHD7 and CHD8, two members of subclass III whose biological function remains largely unknown in lung cancer, for subsequent pathway and function enrichment in LUAD and LUSC." (PMID 35467222, 2022). "In addition, six hub genes that were related to lung cancer were identified as hub genes, including mTOR, NF1, CHD7, ETS1, IL-6, and COL1A1." (PMID 36211008, 2022). "The present study identified six hub genes that were related to lung cancer, including mTOR, NF1, CHD7, ETS1, IL-6, and COL1A1, which might be a potential target for lung cancer." (PMID 36211008, 2022). "In conclusion, the present study screened 46 DEMs in GSE17681 and 1029 DEGs in GSE18842 and identified six hub genes related to lung cancer, including mTOR, NF1, CHD7, ETS1, IL-6, and COL1A1, which might be potential targets for lung cancer." (PMID 36211008, 2022).
microcephaly (2 papers, 2017 to 2020). A congenital or acquired developmental disorder in which the circumference of the head is smaller than normal for the person's age and sex. "Tcf4 binds together with microcephaly-associated transcription factors Smad4, Sox2, Chd7 and Ep300 to active enhancers at primary microcephaly genes Mcph1 and Wdr62." (PMID 28375211, 2017).
myopia (2 papers, 2022 to 2024). "Recent studies in animal models of CHD7 deficiency, as well as GWAS studies implicating CHD7 variants in myopia, point to a potential role for CHD7 in the developing retina and in retinal cell type differentiation or maintenance." (PMID 36172288, 2022). "Given that retinal signals drive eye growth, and abnormalities in the photoreceptor cell layer are associated with myopia development, this suggests that altered CHD7 expression or function may contribute to a broader spectrum of retinal defects than has been previously appreciated." (PMID 36172288, 2022).
pancreatic ductal adenocarcinoma (2 papers, 2016 to 2017). An infiltrating adenocarcinoma that arises from the epithelial cells of the pancreas. "In addition, intriguingly, low-expression of CHD7 was correlated to the survival of gemcitabine treated pancreatic ductal adenocarcinoma patients, suggesting the potential of CHD7 as a tumor suppresser gene like CHD5 in some tumors." (PMID 27955690, 2016).